TFCP2 (transcription factor CP2)
Description:
Binds a variety of cellular and viral promoters including fibrinogen, alpha-globin, SV40 and HIV-1 promoters. Activation of the alpha-globin promoter in erythroid cells is via synergistic interaction with UBP1 (By similarity). Functions as part of the SSP (stage selector protein) complex. Facilitates the interaction of the gamma-globin genes with enhancer elements contained in the locus control region in fetal erythroid cells. Interacts by binding to the stage selector element (SSE) in the proximal gamma-globin promoter.
Synonyms: LSF; SEF; CP2; LBP-1C; TFCP2C; LBP1C; LSF1D
Tractability: PROTAC: ubiquitination databases record sites on it; its protein half-life has been measured.
Gene: Protein-coding gene on chromosome 12 (51,093,656 to 51,173,137, reverse strand). Ensembl gene ENSG00000135457.
Subcellular location: Nucleus
Subcellular location (Human Protein Atlas): Nucleoplasm; Cytosol
Gene Ontology:
Molecular function: cis-regulatory region sequence-specific DNA binding; protein binding; sequence-specific double-stranded DNA binding; transcription factor binding; DNA binding; DNA-binding transcription activator activity, RNA polymerase II-specific; DNA-binding transcription factor activity; DNA-binding transcription factor activity, RNA polymerase II-specific; RNA polymerase II cis-regulatory region sequence-specific DNA binding; transcription cis-regulatory region binding
Biological process: mRNA transcription by RNA polymerase II; positive regulation of transcription by RNA polymerase II; regulation of transcription by RNA polymerase II
Cellular component: nucleoplasm; nucleus; protein-containing complex; chromatin
Genetic constraint (gnomAD): Loss-of-function variants: 21 observed, 53.64 expected, observed/expected ratio (o/e) 0.39, 90% interval 0.28 to 0.56. The upper end of that interval is the gene's LOEUF score, 0.56, which puts it in group 2 of 6, group 1 being the genes least tolerant of losing a copy. Missense variants: 291 observed, 503.43 expected, observed/expected ratio (o/e) 0.58, 90% interval 0.52 to 0.64. Synonymous variants: 165 observed, 182.4 expected, observed/expected ratio (o/e) 0.9, 90% interval 0.8 to 1.03.
Homologues: Orthologues: chimpanzee TFCP2 (100% identical), dog TFCP2 (99% identical), macaque TFCP2 (99% identical), pig TFCP2 (99% identical), rat Tfcp2 (97% identical), mouse Tfcp2 (97% identical), guinea pig TFCP2 (96% identical), tropical clawed frog tfcp2 (92% identical), zebrafish tfcp2 (89% identical), Drosophila melanogaster gem (45% identical), Caenorhabditis elegans grh-1 (21% identical). Paralogues in human: UBP1 (73% identical), TFCP2L1 (70% identical), GRHL2 (26% identical), GRHL1 (26% identical), GRHL3 (25% identical).
Diseases named in the same sentence as TFCP2 in open-access papers:
TFCP2 is named in the same sentence as 56 diseases in open-access papers, as found by Europe PMC text mining. Sharing a sentence is not in itself a finding about the gene and the disease. The quoted sentences say what the papers report.
rhabdomyosarcoma (14 papers, 2021 to 2025). A rare aggressive malignant mesenchymal neoplasm arising from skeletal muscle. "The translocation of TFCP2 (usually exon 2) with either FET family member—EWSR1 (usually exon 5) or FUS (usually exon 6)—most often results in an epithelioid variant of rhabdomyosarcoma." (PMID 40361368, 2025). "In the absence of molecular analysis, strong cytokeratin immunoreactivity in such lesions comprises a major diagnostic pitfall with many TFCP2-rearranged rhabdomyosarcomas previously misinterpreted as spindle cell SCC." (PMID 40526340, 2025). "Examples include HEY1-NCOA2 in mesenchymal chondrosarcoma, IDH1/2 mutations in chondrosarcoma and TFCP2 rearrangements in rhabdomyosarcoma." (PMID 35875137, 2022). "Epithelioid and spindle rhabdomyosarcoma (ES-RMS) with TFCP2 rearrangement is a recently discovered rare variant of rhabdomyosarcoma composed of epithelioid and spindle cells, because it shows extraordinarily adverse prognosis and is easily misdiagnosed as other epithelioid or spindle cell tumors." (PMID 36998041, 2023). "Virtually all examples of TFCP2-rearranged rhabdomyosarcoma are diffusely positive for pancytokeratins, e.g., AE1/AE3, OSCAR, MNF116, and desmin, as well as myogenin and/or MYOD1, with MYOD1 showing higher sensitivity." (PMID 40526340, 2025). "Other non-osteosarcomatous malignancies occurring in the jawbones primarily included conventional and mesenchymal chondrosarcoma, Ewing sarcoma, TFCP2::EWSR1-rearranged rhabdomyosarcoma, and odontogenic neoplasms such as ameloblastic fibrosarcoma." (PMID 40526340, 2025). "Background/Objectives: The fusion of the TFCP2 gene with either EWSR1 or FUS typically results in a spindle cell and/or epithelioid variant of rhabdomyosarcoma." (PMID 40361368, 2025). "Spindle cell/sclerosing rhabdomyosarcomas typically harbor certain genomic alterations, including rearrangements involving TFCP2, VGLL2, NCOA2, CITED2, TEAD1, and SRF, as well as the MYOD1 p.L122R mutation." (PMID 40361368, 2025). "An example of this is the frequent coexpression of pankeratin and ALK in FET::TFCP2 fusion aggressive rhabdomyosarcomas and the frequent expression of EMA and keratins (in addition to occasional ALK, MUC4, etc.)in FET::CREB fusion intra-abdominal neoplasms." (PMID 39249507, 2024). "The molecular characteristics and therapeutic vulnerabilities of TFCP2-rearranged rhabdomyosarcomas (RMS) require further exploration." (PMID 38168093, 2024). "And also recent characterization of spindle cell/sclerosing rhabdomyosarcoma with TFCP2 rearrangement or MEIS-NCOA2 fusion that have been related to bone tumors." (PMID 36173721, 2022). "The following entities will be covered: conventional chondrosarcoma, mesenchymal chondrosarcoma, chordoma, osteosarcoma (high- and low-grade), TFCP2 rearranged rhabdomyosarcoma, odontogenic sarcoma, and odontogenic carcinosarcoma." (PMID 35875137, 2022). "Rhabdomyosarcoma with TFCP2 rearrangement (TFCP2-RMS) is a newly described bone sarcoma characterised by the fusion of TFCP2 to either EWSR1 or FUS showing a remarkable predilection for the craniofacial bones, mainly the mandible and the maxilla." (PMID 35875137, 2022). "Rhabdomyosarcomas with TFCP2 fusions comprise an extremely rare and aggressive type of cancer." (PMID 40361368, 2025). "Similarly, osteosarcoma comprised the most common OSTJS histotype in the pediatric population (8, 53.3%), followed by Ewing sarcoma (4, 26.7%) and 1 each (6.7%) of TFCP2::EWSR1-rearranged rhabdomyosarcoma, mesenchymal chondrosarcoma, and alveolar soft part sarcoma." (PMID 40526340, 2025). "Rhabdomyosarcoma with TFCP2 rearrangement (TFCP2-RMS) is a high-grade rhabdomyosarcoma, characterized by a fusion of TFCP2 to EWSR-1 or FUS." (PMID 35059992, 2022).
hepatocellular carcinoma (13 papers, 2015 to 2024). A malignant tumor that arises from hepatocytes. "TFCP2 has known oncogenic roles in hepatocellular carcinoma, pancreatic adenocarcinoma and BC; it has roles in maintaining cell stemness and in EMT and angiogenesis." (PMID 39478117, 2024). "TFCP2 is correlated with multiple cancers; it is a cancer-promoting factor for hepatocellular carcinoma, pancreatic cancer, and breast cancer, and can also be used as a tumor suppressor, such as inhibiting the growth of melanoma." (PMID 37771430, 2023). "TFCP2 has been studied most extensively in hepatocellular carcinoma (HCC) where it is overexpressed in 90% of HCC cases and correlates with disease progression." (PMID 37061003, 2023). "Previous studies have identified TFCP2 as a pro-cancer factor in hepatocellular carcinoma, pancreatic cancer, breast cancer, and CRC." (PMID 36741376, 2022). "By contrast, the rank of E2F1, GABP and TFCP2 in regulation of gene networks in liver carcinomas strongly increased from GE1-HCC to GE2-HCC." (PMID 33541355, 2021). "In cacer-related studies, TFCP2 was reported to act as an oncogene in hepatocellular carcinoma, pancreatic cancer, and colorectal cancer." (PMID 29423052, 2018). "The expression of TFCP2 has been reported as the oncogene and elevated in the hepatocellular carcinoma (HCC) and colon cancer." (PMID 29050300, 2017). "TFCP2 is an oncogene and plays crucial roles in the incidence and progression of hepatocellular carcinoma (HCC)." (PMID 28348581, 2017). "Transcription factor CP2 (TFCP2) is overexpressed in hepatocellular carcinoma(HCC) and correlated with the progression of the disease." (PMID 25609232, 2015). "Substantially enhanced expression of TFCP2 in hepatocellular carcinoma has been shown to promote oncogenesis." (PMID 25609232, 2015). "The TFCP2/TFCP2L1/UBP1 TF subfamily is involved in various aspects of cancer development, including roles as pro-oncogenic factors in hepatocellular carcinoma as well as pancreatic and breast cancer." (PMID 33892791, 2021).
melanoma (11 papers, 2016 to 2024). A malignant, usually aggressive tumor composed of atypical, neoplastic melanocytes. "The circITCH/miR‐660/TFCP2 axis is involved in melanoma progression hence circITCH can be a diagnostic biomarker as well as a target for treating melanoma." (PMID 35274492, 2022). "Summarily, this research disclosed the circITCH/miR‐660/TFCP2 axis role in melanoma and circITCH represented a novel diagnostic biomarker and potential targets for treating melanoma." (PMID 35274492, 2022). "Additionally, TFCP2 has been implicated in cancer progression and may play a role in melanoma growth." (PMID 37061003, 2023). "A375 TFCP2 knockout human melanoma cells have decreased expression of HS3ST3A1 and HS6ST2 and increased expression of SULF1 and SULF2 what allowed the authors to state TFCP2 as a novel transcriptional regulator of HS biosynthesis." (PMID 39318629, 2024). "The mechanism for these changes in gene expression is in part due to induction of Tfcp2l1, a member of the TFCP2/TFCP2L1/UBP1 transcription factor subfamily that can serve as a pro-oncogenic factor in some tumors or in the case of melanoma, a tumor suppressor." (PMID 37270599, 2023). "To investigate the role of TFCP2 in HS assembly, we targeted TFCP2 expression in human melanoma cells using the CRISPR/Cas9 system." (PMID 37061003, 2023). "In this study, CRISPR/Cas9 targeting of TFCP2 in human melanoma cells led to distinct changes in HS gene expression and growth factor binding at the cell surface." (PMID 37061003, 2023). "This earlier report found that transient overexpression of TFCP2 in mouse melanoma cells gave a decrease in 3D growth and tumor growth in vivo, respectively." (PMID 37061003, 2023). "Future studies will be focused on investigating the TFCP2/SULF1 regulatory axis as a viable drug target in melanoma and other tumor types." (PMID 37061003, 2023). "In previous studies, genome-wide CRISPR/Cas9 screening assays in A375 human melanoma cells identified the alpha-globin transcription factor, TFCP2, as a potential regulator of HS assembly." (PMID 37061003, 2023). "In the present study, we investigated the regulatory role of TFCP2 in HS assembly by targeting this factor in A375 human melanoma cells." (PMID 37061003, 2023). "Overall, these studies identify TFCP2 as a novel transcriptional regulator of HS and highlight HS–protein interactions as a possible target to slow melanoma growth." (PMID 37061003, 2023). "A few studies have reported that TFCP2 not only promotes but also inhibits cancers such as melanoma and has some important physiological functions that have not yet been discovered." (PMID 35193647, 2022). "And there is a positive correlation between the expression of TFCP2 and circITCH in melanoma tissues, indicating that miR‐660 and its target genes TFCP2 are both regulated by circITCH in melanoma." (PMID 35274492, 2022). "The mechanism study showed that circITCH‐sponged miR‐660 to upregulate TFCP2 and suppress melanoma progression." (PMID 35274492, 2022). "Overall, our study shows that circITCH is a tumorigenesis suppressor in melanoma, mechanistically by controlling cascades of the miR‐660/TFCP2 pathway." (PMID 35274492, 2022). "Mechanism study demonstrated that circITCH‐sponged miR‐660 to upregulate TFCP2 and suppress melanoma progression." (PMID 35274492, 2022). "To support whether the FGF1 binding defect was specific to human melanoma cells, we knocked down TFCP2 expression in a panel of patient-derived malignant melanoma tumor lines with diverse genotypes (SkMel2, SkMel5, SkMel28, and UACC62)." (PMID 37061003, 2023). "Interestingly, the inactivation of TFCP2 in A375 cells reduced their 2D and 3D growth, which is contrary to a previous study showing that overexpression of TFCP2 inhibits melanoma cell growth." (PMID 37061003, 2023). "TFCP2 could be a pro‐oncogenic feature in the liver, pancreatic, and breast cancers, and it could also be a tumor suppressor to inhibit melanoma growth." (PMID 35274492, 2022).
melanoma (continued). "Moreover, we detected the TFCP2 expression in 30 melanoma and adjacent normal tissue pairs and found it downregulated in melanoma." (PMID 35274492, 2022). "Here, we found that TFCP2 was downregulated in melanoma tissues." (PMID 35274492, 2022). "This demonstrates that circITCH‐sponged miR‐660 controls expressing TFCP2 in melanoma." (PMID 35274492, 2022). "However, the expression of TFCP2 was reported to be down-regulated in melanoma tissues, and over-expression of TFCP2 inhibited the anchorage-independent growth of melanoma cells through P21 pathway." (PMID 29050300, 2017). "Therefore, we knocked down TFCP2 expression using RNA interference in A375 (melanoma), HeLa (cervical adenocarcinoma), A549 (lung carcinoma), Hep3B (liver hepatocellular carcinoma), and MDA-MB-231 (triple negative breast adenocarcinoma) cells and measured FGF1 binding and SULF1 expression." (PMID 37061003, 2023). "Interestingly, transgenic overexpression of TFCP2 in melanoma was shown to impede tumor growth." (PMID 37061003, 2023). "Altogether, these results suggest that TFCP2 may play a unique HS regulatory role in melanoma." (PMID 37061003, 2023). "Additionally, TFCP2 acts as a tumor suppressor, inhibiting the development of melanoma." (PMID 36741376, 2022). "Overall, our results, as well as clinical patient data, suggest that TFCP2 and SULF1 should be further explored as potential targets for melanoma therapy." (PMID 37061003, 2023). "Nonetheless, TFCP2 can also act as a TSG, as exemplified by its capacity to inhibit melanoma growth." (PMID 33892791, 2021). "TFCP2-mediated repression of SULF1 may link these observations, and our data showing that knockdown of SULF1 increases melanoma cell growth correlate well with these findings." (PMID 37061003, 2023). "Pharmacological targeting of TFCP2 activity similarly reduced growth factor binding and increased SULF1 expression, and the knockdown of SULF1 expression in TFCP2 mutant cells restored melanoma cell growth." (PMID 37061003, 2023). "To determine whether the expression of TFCP2 and/or SULF1 correlate with the survival of patients with melanoma, we analyzed clinical data from the TCGA database using the University of Alabama at Birmingham UALCAN interactive web portal." (PMID 37061003, 2023).
sarcoma (11 papers, 2019 to 2025). A usually aggressive malignant neoplasm of the soft tissue or bone. "TFCP2 fusion sarcomas are associated with poor outcomes, high rates of recurrence, and treatment resistance." (PMID 40361368, 2025). "A diagnosis of craniofacial tumor in young males with biopsy suggesting an intraosseous sarcoma should point towards testing for TFCP2 mutation." (PMID 41497928, 2025). "This study also found that many TFCP2 fusion sarcomas have CDKN2A loss." (PMID 40361368, 2025). "TFCP2 fusion sarcomas are associated with extremely poor prognosis." (PMID 40361368, 2025). "The fourth gene deregulated in TFCP2-rearranged sarcoma, besides ALK, CDKN2A, and MTAP, is TERT, encoding the catalytic component of the telomerase complex that protects dividing cells from progressive telomere shortening, subsequent senescence, and malignant transformation." (PMID 38168093, 2024). "In summary, we report our experience with 10 cases of TFCP2 fusion sarcomas and review the literature of 53 total cases." (PMID 40361368, 2025). "In reviewing the literature, we identified 53 cases of TFCP2 fusion sarcomas, including the 10 reported herein." (PMID 40361368, 2025). "In the present study, we sought to understand the clinical characteristics, efficacy of treatments, and clinical outcomes in patients with TFCP2 fusion sarcomas." (PMID 40361368, 2025). "Herein, we report the clinical characteristics, treatments, and outcomes of 10 patients with TFCP2 fusion sarcomas from a single institution." (PMID 40361368, 2025). "Herein, we describe the clinical characteristics and treatment course of 10 patients with TFCP2 fusion sarcomas." (PMID 40361368, 2025). "We also review the 53 total cases of TFCP2 fusion sarcomas in the literature, again highlighting the dismal outcomes in this disease." (PMID 40361368, 2025). "Together, these data suggested that TFCP2 fusions contribute to the development of genomically unstable sarcoma by impairing the DNA repair machinery." (PMID 38168093, 2024). "Unexpectedly, the TFCP2-rearranged cases were more closely related to undifferentiated sarcomas than other RMS subgroups." (PMID 38168093, 2024). "The frequent overexpression of wildtype (WT) ALK and/or ALK variants suggested that these events are critical for the pathogenesis of TFCP2-rearranged sarcoma." (PMID 38168093, 2024). "The TFCP2 fusion positive subtype of SCS-RMS has initially been identified through RNA sequencing of sarcoma samples." (PMID 36551545, 2022). "We identified 10 patients with confirmed TFCP2 fusion-positive sarcomas." (PMID 40361368, 2025). "Additional work is needed to define the optimal treatment course for TFCP2 fusion sarcomas." (PMID 40361368, 2025). "However, several cases of TFCP2 fusion sarcoma reported in the literature have noted lymph node involvement, and 5 of the 10 patients described herein had lymph node involvement." (PMID 40361368, 2025). "Whether the role of IGFBP5 in TFCP2-rearranged sarcoma depends on IGF signaling and is mediated via the full-length protein or proteolytic fragments remains to be determined." (PMID 38168093, 2024). "DNA methylation analysis supported this relationship, indicating that the categorization of sarcomas with TFCP2 fusions as RMS should be revisited and underscoring the potential of multilayered molecular profiling to refine and sometimes revise conventionally defined disease categories." (PMID 38168093, 2024). "First, we found high expression of IGFBP5 in TFCP2-rearranged sarcoma." (PMID 38168093, 2024).